FOXP3 (forkhead box P3)
Diseases named in the same sentence as FOXP3 in open-access papers (continued):
Sharing a sentence is not in itself a finding about the gene and the disease.
cancer (continued). "The influence of CD4+CD25+Foxp3+ regulatory T-cells (Tregs) on cancer progression has been demonstrated in a large number of preclinical models and confirmed in several types of malignancies." (PMID 24133490, 2013). "In contrast, FOXP3 appears to be expressed in normal epithelial cells of human breast and prostate, but downregulated in the corresponding cancer cells." (PMID 24350059, 2013). "The mean value of Foxp3+ cancer cell expression by immunohistochemical analysis for all studied tissue samples of the 65 tumors was determined at 16%." (PMID 23382847, 2013). "Considering the Foxp3+ cancer cell expression as a continuous variable, regression analysis showed that Foxp3+ cancer cell expression had a weak but significant inverse correlation with the Foxp3+ Treg expression (R2 = 0.17, p = 0.01, n = 65; r = −0.41)." (PMID 23382847, 2013). "First we demonstrated Foxp3 expression in cancer cells of patients with CRC using immunofluorescence double staining." (PMID 23382847, 2013). "But also, FOXP3 is an important tumor suppressor factor in some types of cancers, and therefore, understanding the structure and function of FOXP3 is crucial to gaining insights into the development of FOXP3-targeted therapeutic strategies." (PMID 24350059, 2013). "It is well established that FOXP3 nuclear expression is constitutive in human Tregs and nuclear localization is also observed in many normal and cancer cells wherein it acts as a transcription factor." (PMID 23341929, 2013). "Among patients with CRC, those with high Foxp3+ cancer cell expression (>16%) had a poorer prognosis than those with low Foxp3+ expression levels (<16%) (p<0.001, Log-Rank test)." (PMID 23382847, 2013). "In this study, we identified lymphocyte-specific protein tyrosine kinase (LCK), which correlates with cancer malignancy, as a binding partner of FOXP3." (PMID 24155921, 2013). "From current knowledge, the composition of Foxp3+ Treg cells within tumors and/or in circulation in human cancer patients remains poorly understood." (PMID 23874336, 2013). "Several groups observed Foxp3 expression by various cancer types and its potential role on immune surveillance by producing immunosuppressive cytokines such as IL-10 and TGF-β." (PMID 23382847, 2013). "Regarding the expression of FOXP3 in human cancer cells and in their normal homologs, two opposite situations have been found." (PMID 24350059, 2013). "Immunofluorescence double staining indicated the expression of the immunosuppressive cytokines IL-10 and TGF-β in Foxp3+ expressing cancer cells (arrows)." (PMID 23382847, 2013). "In contrast, in the breast and prostate, FOXP3 is expressed in normal epithelial cells but down-regulated in corresponding cancer cells." (PMID 23888189, 2012). "Taken together, our results suggest that the impact of FTS-induced Ras inhibition on Foxp3 expression in the immune system differs from its impact on Foxp3 expression in cancer cells." (PMID 22323550, 2012). "In the immune cells it leads to upregulation of Foxp3, whereas in cancer cells it leads to Foxp3 downregulation (see scheme in Figure." (PMID 22323550, 2012). "Complex interactions between effector T cells and Foxp3+ regulatory T cells (Treg) contribute to clinical outcomes in cancer, and autoimmune and infectious diseases." (PMID 23029447, 2012). "Elevated levels of regulatory T cells (Tregs), usually characterised as CD4+, CD25+ and/or transcription factor forkhead box P3 (FoxP3) cells, has been widely reported to prevent the immunological clearance of many types of cancer." (PMID 24213326, 2012). "Among the different activated DC populations, Poly I:C-activated DCs that were generated in CellGro had the lowest ratio FoxP3+ Tregs/antigen specific T cells and thus appear to be the most suitable cells for use in DC cancer immunotherapy studies." (PMID 22208910, 2011).
cancer (continued). "Integrating analysis of FOXP3 with the cell-surface molecule CD127 clearly demonstrates that significantly higher numbers of CD127lowFOXP3+ Treg cells are expanded in cancer patients in general." (PMID 21904560, 2011). "Although FoxP3 is still regarded as the most reliable marker of Tregs in human cancer, it can also be expressed by epithelial tumor cells and in vitro activated CD4+ and CD8+ T cells." (PMID 19641607, 2009). "This study provides clear evidence that cancer cells of various types express a transcript for Foxp3 as well as the mature protein." (PMID 18430198, 2008). "Recently, intratumoral Foxp3+ T regs in ovarian or pancreatic cancer were correlated with a poor prognosis." (PMID 18087278, 2008). "Recent studies have demonstrated a direct involvement of B7-H1, PD-1 and FOXP3 molecules in the immune escape of cancer." (PMID 18294387, 2008). "We have used FOXP3 as a detection marker for Tregs as it became recently a biomarker for studying Tregs in malignant human cancers." (PMID 18294387, 2008). "FOXp3 belongs to the forkhead gene family which comprises a diverse group of "winged-helix" TFs with important roles in development, metabolism, cancer and aging." (PMID 16420690, 2006). "In contrast, other types of T cells that favor cancer progression and shorten survival may be present, such as regulatory T cells (such as Foxp3) and CD4 helper 2 cells." (PMID 39858287, 2025). "In addition, the mRNA expression of CD8, CD4, and Foxp3 was measured with RT-qPCR to evaluate the overall T-cell infiltration in the TME of cancer tissues." (PMID 39917292, 2025). "FOXP3 expression patterns varied significantly between cancer subtypes and stages." (PMID 39857011, 2025). "We used ImmunoProfile to prospectively capture and quantify four key biomarkers associated with an active (CD8 and PD-1) and suppressed (FOXP3 and PD-L1) immune response in FFPE tissues from 2,023 patients presenting to a tertiary care cancer center over 3.25 years." (PMID 40906987, 2025). "PDACs might also overexpress FOXP3 (the master regulatory transcription factor driving Treg development/function), and cancer-FOXP3 was found to directly activate CCL5." (PMID 40723238, 2025). "Foxp3-positive regulatory T cells (Treg) also play an important role in the IgG4 response and may lead to a poor prognosis through the immune evasion of cancer." (PMID 40563656, 2025). "However, we considered FOXP3 a suitable marker for IHC evaluation of Tregs infiltration in CC as TILs and cancer cells are easily distinguished by morphological features, as has already been shown for other solid cancers." (PMID 41007768, 2025). "Notably, CASP1 was consistently elevated in normal tissues across most cancers, whereas FOXP3 and PDIA3 were frequently enriched in tumors." (PMID 41150760, 2025). "In addition, AZD5582 enhances the infiltration of CD8-positive T cells and decreases the infiltration of Foxp3-positive Treg cells in the TME of cancer tissues of immune-intact C57BL/6 mice." (PMID 39917292, 2025). "Additionally, NP1192 combined with anti-PD-L1blockade also significantly reduced cancer-promoting Tregs (CD4+CD25+FOXP3+), compared to the anti-PD-L1or NP1192 alone groups." (PMID 41341045, 2025). "Development in antisense oligonucleotide technology and RNA-targeting small molecules have proven that ncRNA is a ‘druggable’ molecule amenable for therapeutic treatment and FOXP3 RNA has recently been reported to be a viable ASO target in a mouse cancer model." (PMID 40605177, 2025). "The prognostic value of FOXP3 remains controversial across different cancer types." (PMID 40806346, 2025). "T regulatory (Treg) cells are a subset of CD4+ T cells that express the forkhead box P3 (Foxp3) transcription factor, promoting immune tolerance and preventing autoimmune reactions; however, their role can have paradoxical implications in cancer." (PMID 40951642, 2025).
cancer (continued). "Consequently, the cancer cells multiply in an immune-suppressive environment where FOXP3+ Tregs are increased in number, while effector T cells and dendritic cells (DCs) activities become ineffective." (PMID 39940924, 2025). "This may have functional impact when considering targeting FOXP3 in cancer therapy both with respect to cancer cells as well as in T regs." (PMID 39099201, 2024). "All 5 ASOs significantly downregulated FOXP3 mRNA expression in primary cancer samples." (PMID 39234236, 2024). "First, we could not achieve binding of endogenous or exogenous FOXP3 sufficient for ChIP sequencing analysis, which would complement our gene expression studies on the broader role of FOXP3 in cancer cells." (PMID 39099201, 2024). "While the causative link between IPEX and oncogenesis remains elusive, alterations in T cells homeostasis and reduced expression of FOXP3 in the epithelial cells may have played a role in the development of this patient's cancer." (PMID 39475830, 2024). "Expression of innate immune system markers (APOBEC3A/B), DNA repair genes (BRCA1, BRCA2, PALB2, RAD51), cell cycle genes (CCNA2 and CCNE1), a cell proliferation gene (MELTF), and a T-cell regulator (Treg) marker (FOXP3) was elevated in cancer compared to precancer and controls." (PMID 39672307, 2024). "In contrast, in the context of cancer, a distinctive subset known as Vδ2 Tregs, which are specific types of γδ T cells with regulatory activities and Foxp3 expression, can be induced in the presence of antigen stimulation (IPP/IL-2) and TGF-β1 and IL-15 cytokines in vitro." (PMID 38983267, 2024). "Based on our findings, potential targeting of FOXP3 may impact PD-L1 expression and other immune checkpoints, as well as other cancer cell intrinsic functions in promoting EMT." (PMID 39099201, 2024). "However, in this study, we confirmed FoxP3 expression in the cancer cells themselves, as was evident in the CC group." (PMID 39150932, 2024). "Specific TIL subsets that have been shown to be associated with cancer prognosis vary across the studies and include CD3+, CD4+, CD5+, CD8+, CD45RA+, FOXP3+ and PD1+ TILs; however, CD3+, CD8+ and FOXP3+ TILs were commonly shown to associate with prognosis in many cancer types." (PMID 38704243, 2024). "The immunomodulatory effects of FoxP3 cells in cancer include suppression of the immune response." (PMID 38962703, 2024). "However, previous evidence suggested that FOXP3 can be detected in various cancers and plays dual roles in cancer pathogenesis." (PMID 38041531, 2024). "The consequence of any therapy against FOXP3 will need to acknowledge its effect in cancer cells as well as well-established roles in T regulatory cell function, which in itself has been a focus of cancer therapy." (PMID 39099201, 2024). "Gut-derived SCFAs have been found to promote regeneration and proliferation of Tregs in cancer patients, including butyrate and propionate (PA) mediated Tregs differentiation through activating Foxp3 intronic enhancer CNS1 and increasing histone H3 acetylation levels." (PMID 38644503, 2024). "Notably, a robust correlation between cTOB1/nTOB1 and FOXP3 expression was observed in the cancer tissues (R = 0.41 and R = 0.38)." (PMID 38617839, 2024). "FOXP3+ Tregs also infiltrate tumors and enable cancer cells to evade the immune system." (PMID 39770446, 2024). "Additionally, FoxP3 in cancer cells plays a dual role in malignant transformation as a cancer promoting factor and in suppressing cancer by inhibiting the transcription of downstream oncogenes and related target genes." (PMID 39150932, 2024). "CD8 and FOXP3 play important but opposite roles in cancer and are two specific subgroups of TILs." (PMID 38352864, 2024). "Additionally, the amount of FOXP3 protein per cell in leftover Tregs in cancer samples decreased more significantly than in PBMC samples and in transplant lungs." (PMID 39234236, 2024).
cancer (continued). "Reduced Foxp3 expression is advantageous for enhancing the therapeutic benefit of patients on anti-cancer medications, as miR-4281 directly binds to the Foxp3 promoter, upregulates the expression of Foxp3 protein, and promotes the immunosuppressive role of Foxp3+Treg." (PMID 38919615, 2024). "Recent studies have found FoxP3 expression in invasive Tregs and various cancer cells." (PMID 39150932, 2024). "Furthermore, in the in vivo model, a higher expression of PAK4 was associated with the increased peritumoral infiltration of immune cells related to the immune evasion of cancer cells, FOXP3-, and PD1-positive cells." (PMID 39273017, 2024). "The observed alterations in FOXP3 expression suggest that these agents may effectively disrupt immune evasion mechanisms commonly employed by cancer cells, thereby sensitizing them to chemotherapy." (PMID 39770446, 2024). "EGFR Tyrosine kinase inhibitors (TKIs) can enhance the effect of MHC class I and II antigens on IFN-γ to increase CD8+T cells and DC cells levels, eliminate FOXP3+Tregs, inhibit Macrophage polarization to M2 phenotype, and reduce the PD-L1 expression in cancer cells." (PMID 37799727, 2023). "Moreover, a substantial enrichment of CD4+, CD4+PD‐1+, and Foxp3+ phenotypes cell populations near cancer cells were observed in UnTx compared to IP CD40 and NDES CD40 (dotted black rectangle; rows 11, 12, and 13, respectively, and column 21)." (PMID 36658712, 2023). "FoxP3+ natural Treg cells are generated in the thymus as a functionally mature T cell subpopulation specialized in immune suppression, hindering immunosurveillance against cancer development and hampering effective anti-tumor immune responses." (PMID 37529610, 2023). "Regulatory CD8+ T cells have been characterized, such as CD8+ Qa-1-restricted suppressor cells, which have also been implicated in self-tolerance and allograft acceptance, and CD8+ Foxp3+ regulatory cells, which have been described in both cancer and transplantation contexts." (PMID 38993904, 2023). "However, there are numerous reports showing that the FOXP3 lymphocytes in CRC are substantially different from those in other human cancers." (PMID 37960147, 2023). "Therefore, the dual role of FOXP3 in cancer is advantageous for HNSCC patients, and this positive impact is probably enhanced by CMTM6." (PMID 38067301, 2023). "In particular, the metastatic ecosystem was found to feature remarkable reprogramming of immunosuppressive cells such as FOXP3+ Treg cells, LAMP3+ tolerogenic DCs, CCL18+ M2‐like macrophages, RGS5+ cancer‐associated fibroblasts (CAFs), and LGALS1+ microglial cells." (PMID 36529697, 2023). "LINC00853 exerted a cancer-promoting role in GC through FOXP3-mediated transcription of PDZK1IP1." (PMID 37403034, 2023). "Expression of Foxp3 in human cancer cells and BPV1-infected sarcoid fibroblasts raised the question of whether Foxp3 may confer immune regulatory functions to these cells." (PMID 37112681, 2023). "The different roles of FOXP3 in cancer cells may be partly related to the alternative splicing which seems to produce more short isoforms than in normal cells." (PMID 37868998, 2023). "FOXP3+ T cell might suppress the activity of cytotoxic T cells via cytokines; therefore, high-infiltration with FOXP3+ TILs is correlated with poor prognosis in several cancers." (PMID 36693070, 2023). "In addition to its basic role in immune responses, FOXP3 also plays a significant role in cancer development." (PMID 37176567, 2023). "Forkhead box P3 (Foxp3) also has a similar effect on cancer cells." (PMID 36544523, 2022). "In addition to Treg cells, Foxp3 is also expressed in cancer cells and promotes cancer growth and metastasis." (PMID 36316775, 2022). "Across cancer types and for IHC, there was a general consensus in favor of FOXP3 staining." (PMID 35740658, 2022). "Overexpression of FOXP3 significantly induces cancer cell proliferation, migration, and invasion." (PMID 35309319, 2022).
cancer (continued). "FOXP3 was found to impede DNA damage repair in cancer cells, which might contribute to its participation in tanshinone IIA-induced pyroptosis." (PMID 36387211, 2022). "Nonetheless, all the previous reports suggest functional and prognostic heterogeneity within the group of FoxP3+ TILs, which could be an innate feature of this cell type not limited to specific cancer entities." (PMID 35140715, 2022). "Moreover, it is less clarified that TAM is also involved indirectly via a Foxp3 knockout model through the CreER system to target specific immune checkpoints, especially checkpoints arising in cancer therapy." (PMID 36009853, 2022). "Analysis of RNA-seq data sets revealed positive correlations between Vtcn1, the gene name of B7x, and Foxp3 in multiple human cancers, as well as a highly statistically significant correlation in a pan-cancer analysis of 30 cancer types curated by The Cancer Genome Atlas (TCGA)." (PMID 35523809, 2022). "Additionally, since the expression of NR4As is necessary for the maintenance of FOXP3 expression by Tregs, there have been reports of several studies where those genes are targeted to modulate Treg responses in cancer." (PMID 36499469, 2022). "EGFR-Tyrosine Kinase Inhibitors (TKIs) strengthen MHC class I and II antigen presentation in response to IFN-γ, boost CD8+ T-cells levels and DCs, eliminate FOXP3+ Tregs, inhibit macrophage polarization into the M2 phenotype, and decrease PD-L1 expression in cancer cells." (PMID 35742933, 2022). "Indeed, glucocorticoid induced tolDCs were also seen to elevate the CD8+ Treg (FoxP3+) numbers in the context of cancer and human CD14+ monocytes displayed a similar behavior." (PMID 35784310, 2022). "According to the density and distribution of CD8+ T cells and FOXP3+ regulator T (Treg) cells etc, which determine the classification of “hot” versus “cold” tumors, the clinical outcome of various cancer patients can be predicted: “hot” tumors have potential sensitivity to immunotherapy." (PMID 35222387, 2022). "FOXP3 promotes immune evasion by inhibiting Treg cell markers of cancer immune response." (PMID 36203616, 2022). "In cancer, the area of interest is not only the expression or the inhibition of Foxp3." (PMID 36009853, 2022). "However, the role of cancer cell FOXP3 in tumorigenesis is conflicting and still warrants further investigation." (PMID 36497433, 2022). "The CD8+/FoxP3+ T cell ratio was commonly studied to predict the prognosis of patients and a meta-analysis indicated that a high CD8+/FoxP3+ T cell ratio was independently associated with improved survival based on the data from multiple cancer types." (PMID 35999614, 2022). "Our comprehension of the interplay between FOXP3+ Treg cells and key hallmarks of cancer may provide new insights into the development of next-generation engineered T cell-based immune treatments for solid tumours." (PMID 36569832, 2022). "Therefore, in this study, we determined the cytokine profile of CD4+ and CD8+ T cells as well as the frequency of Foxp3+ Treg cells in the TDLNs of HNSCC and assessed their association with cancer parameters." (PMID 36376825, 2022). "The immunosuppressive and immune‐resistant properties of FoxP3+Treg cells could encourage immune escape, facilitate carcinoma growth, and reverse CD8+ T killing." (PMID 36301031, 2022). "Since expression of NR4As is necessary for the maintenance of forkhead box P3 (FoxP3) expression and thereby essential for the development of Tregs, there have been reports of several studies where those genes are targeted to modulate Treg responses in cancer." (PMID 33803543, 2021). "FOXP3, a molecular marker of Tregs, is highly expressed in lymphoid tissue, and plays a key role in the development and function of Treg cells, representing an important therapeutic target for cancer." (PMID 34269372, 2021).